YIPF2 (Yip1 domain family member 2)
Synonyms: MGC3262; FinGER2; Yip5C; YIPFbeta3B
Tractability: Antibody: UniProt predicts a signal peptide or a membrane-spanning region. PROTAC: ubiquitination databases record sites on it; its protein half-life has been measured.
Gene: Protein-coding gene on chromosome 19 (10,918,919 to 10,928,681, reverse strand). Ensembl gene ENSG00000130733.
Subcellular location: Golgi apparatus, cis-Golgi network membrane; Golgi apparatus, trans-Golgi network membrane; Late endosome membrane
Subcellular location (Human Protein Atlas): Golgi apparatus; Mitochondria
Gene Ontology:
Molecular function: protein binding; small GTPase binding
Biological process: vesicle-mediated transport
Cellular component: Golgi medial cisterna; Golgi trans cisterna; late endosome membrane; trans-Golgi network; transport vesicle; Golgi apparatus; endomembrane system; membrane
Genetic constraint (gnomAD): Loss-of-function variants: 30 observed, 39.27 expected, observed/expected ratio (o/e) 0.76, 90% interval 0.57 to 1.04. The upper end of that interval is the gene's LOEUF score, 1.04, which puts it in group 4 of 6, group 1 being the genes least tolerant of losing a copy. Missense variants: 401 observed, 416.53 expected, observed/expected ratio (o/e) 0.96, 90% interval 0.89 to 1.05. Synonymous variants: 194 observed, 186.76 expected, observed/expected ratio (o/e) 1.04, 90% interval 0.92 to 1.17.
Homologues: Orthologues: chimpanzee YIPF2 (99% identical), macaque YIPF2 (95% identical), rabbit YIPF2 (84% identical), dog YIPF2 (81% identical), mouse Yipf2 (80% identical), guinea pig YIPF2 (79% identical), rat Yipf2 (79% identical), pig YIPF2 (65% identical), zebrafish yipf2 (48% identical), tropical clawed frog yipf2 (46% identical), Drosophila melanogaster CG4645 (32% identical), Caenorhabditis elegans Y25C1A.7 (30% identical). Paralogues in human: YIPF1 (47% identical).
Diseases named in the same sentence as YIPF2 in open-access papers:
YIPF2 is named in the same sentence as 6 diseases in open-access papers, as found by Europe PMC text mining. Sharing a sentence is not in itself a finding about the gene and the disease. The quoted sentences say what the papers report.
hepatocellular carcinoma (1 paper, 2020). A malignant tumor that arises from hepatocytes. "It has been reported that YIPF2 and its family members are potentially involved in intracellular vesicular transport, and knockdown of its expression promotes the migration of hepatocellular carcinoma cells." (PMID 32303681, 2020). "Besides, YIPF2 can serve as the GDF (GDI-displacement factor) of RAB5/RAB22A, thus catalyzing the dissociation of RAB-GDI complexes and regulating CD147 endocytic recycling finally in hepatocellular carcinoma cells." (PMID 32303681, 2020).
liver cancer (1 paper, 2019). An epithelial or non-epithelial malignant neoplasm that arises from the liver. "Although CD147 and YIPF2 tend to be high-expressed in liver cancer patients, CD147 exhibited a higher transcription level in HCC tissues than in matched normal tissues." (PMID 31189879, 2019).
lung adenocarcinoma (1 paper, 2020). A carcinoma that arises from the lung and is characterized by the presence of malignant glandular epithelial cells. "The data showed that the mRNA levels of YIPF2 were significantly lower in lung adenocarcinoma tissues than that in normal tissues." (PMID 32303681, 2020).
lung carcinoma (1 paper, 2020). "Finally, using bioinformatics database, the YIPF2-TNFRSF10B axis was confirmed to be associated with the malignant progression of lung cancer." (PMID 32303681, 2020). "Collectively, these data reveal that the mRNA expression of YIPF2 and TNFRSF10B is associated with malignant progression in lung cancer patients." (PMID 32303681, 2020). "Finally, YIPF2 expression tended to be positively associated with the expression of TNFRSF10B in two GEO datasets (GDS1688 and GDS3627), which contained 29 lung cancer cell lines and 58 NSCLC cell lines respectively." (PMID 32303681, 2020).
YIPF2 also shares sentences with these, for which no sentence is quoted: non-small cell lung carcinoma (2 papers); colon cancer (1).